OXLD1 (oxidoreductase like domain containing 1)
Synonyms: C17orf90; MGC104712
Tractability: PROTAC: its protein half-life has been measured.
Gene: Protein-coding gene on chromosome 17 (81,665,036 to 81,666,635, reverse strand). Ensembl gene ENSG00000204237.
Subcellular location (Human Protein Atlas): Cytosol; Vesicles
Gene Ontology:
Cellular component: mitochondrion
Genetic constraint (gnomAD): Loss-of-function variants: 12 observed, 7.51 expected, observed/expected ratio (o/e) 1.6, 90% interval 0.97 to 1.94. That is too few expected variants to judge how well the gene tolerates losing a copy. Missense variants: 240 observed, 203.54 expected, observed/expected ratio (o/e) 1.18, 90% interval 1.06 to 1.31. Synonymous variants: 100 observed, 89.55 expected, observed/expected ratio (o/e) 1.12, 90% interval 0.95 to 1.32.
Homologues: Orthologues: chimpanzee OXLD1 (99% identical), macaque OXLD1 (92% identical), dog OXLD1 (67% identical), rat Oxld1 (65% identical), pig OXLD1 (63% identical), guinea pig OXLD1 (62% identical), mouse Oxld1 (60% identical), tropical clawed frog pde6g (32% identical), Drosophila melanogaster CG5500 (27% identical), Caenorhabditis elegans C49A9.10 (16% identical).
Diseases named in the same sentence as OXLD1 in open-access papers:
OXLD1 is named in the same sentence as 1 disease in open-access papers, as found by Europe PMC text mining. Sharing a sentence is not in itself a finding about the gene and the disease. The quoted sentences say what the papers report.
colon cancer (1 paper, 2025). "In conclusion, we have developed a gene expression score, based on ZNF697, CTSC, SNORA2B, and OXLD1, that effectively stratifies patients with stage II colon cancer into low and high‐risk groups, facilitating the identification of patients who may benefit from adjuvant chemotherapy." (PMID 40478186, 2025). "A dichotomized score, derived from the combined expression of four RNAs (ZNF697, SNORA2B, CTSC and OXLD1), effectively predicted TTR in stage II colon cancer patients." (PMID 40478186, 2025).